TASOR (transcription activation suppressor)
Description:
Core component of the HUSH complex, a multiprotein complex that specifically mediates epigenetic repression of mobile genetic elements, such as retroviruses and transposable elements. The HUSH complex represses LINE-1 (L1) retrotransposons that are still capable of transposition. Silencing events often occur within introns of transcriptionally active genes, and lead to the down-regulation of host gene expression. The HUSH complex also represses exogenous retroviruses and synthetic transgenes. The HUSH complex also represses expression of latent herpes simplex virus. Mediates silencing of unintegrated retroviral DNA following recruitment by ZNF638: some part of the retroviral DNA formed immediately after infection remains unintegrated in the host genome and is transcriptionally repressed. The HUSH complex is recruited to genomic loci rich in H3K9me3 and is required to maintain transcriptional silencing by promoting recruitment of SETDB1, a histone methyltransferase that mediates further deposition of H3K9me3, as well as MORC2, a chromatin remodeler that compacts chromatin. Within the HUSH complex, TASOR acts as the central scaffold which recruits MPHOSPH8 and PPHLN1 to mobile genetic elements and mediates association with SETDB1 and MORC2. The ability to silence mobile genetic elements plays a crucial role in early embryonic development: it is required to maintain epiblast cell fitness and cell division (By similarity).
Synonyms: C3orf63; FAM208A; KIAA1105; se89-1; RAP140; TASOR1
Tractability: PROTAC: UniProt records ubiquitination sites on it; ubiquitination databases record sites on it.
Gene: Protein-coding gene on chromosome 3 (56,620,132 to 56,683,265, reverse strand). Ensembl gene ENSG00000163946.
Subcellular location: Nucleus; Chromosome
Subcellular location (Human Protein Atlas): Nucleoplasm
Pathways (Reactome):
Gene expression (Transcription): Regulation of endogenous retroelements by the Human Silencing Hub (HUSH) complex
Gene Ontology:
Molecular function: chromatin binding; protein binding; protein-macromolecule adaptor activity; RNA binding
Biological process: constitutive heterochromatin formation; negative regulation of gene expression, epigenetic; protein localization to heterochromatin; transposable element silencing by heterochromatin formation; anterior/posterior axis specification, embryo; mesodermal to mesenchymal transition involved in gastrulation
Cellular component: chromosome; heterochromatin; HUSH complex; nucleoplasm; nucleus
Genetic constraint (gnomAD): Loss-of-function variants: 42 observed, 143.57 expected, observed/expected ratio (o/e) 0.29, 90% interval 0.23 to 0.38. The upper end of that interval is the gene's LOEUF score, 0.38, which puts it in group 1 of 6, group 1 being the genes least tolerant of losing a copy. Missense variants: 1,640 observed, 1,804.4 expected, observed/expected ratio (o/e) 0.91, 90% interval 0.87 to 0.95. Synonymous variants: 639 observed, 649.01 expected, observed/expected ratio (o/e) 0.98, 90% interval 0.92 to 1.05.
Homologues: Orthologues: chimpanzee TASOR (96% identical), macaque TASOR (94% identical), pig TASOR (91% identical), rabbit TASOR (89% identical), dog TASOR (81% identical), rat Tasor (74% identical), mouse Tasor (74% identical), guinea pig TASOR (69% identical), tropical clawed frog tasor (42% identical), zebrafish tasorb (31% identical), zebrafish tasora (26% identical), Caenorhabditis elegans T11G6.5 (12% identical). Paralogues in human: TASOR2 (16% identical).
Diseases named in the same sentence as TASOR in open-access papers:
TASOR is named in the same sentence as 6 diseases in open-access papers, as found by Europe PMC text mining. Sharing a sentence is not in itself a finding about the gene and the disease. The quoted sentences say what the papers report.
cancer (4 papers, 2017 to 2023). A tumor composed of atypical neoplastic, often pleomorphic cells that invade other tissues. "Whether TASOR might have a role in cell pluripotency, suppression of cell differentiation and, more generally, be linked to cancer progression as demonstrated for EZH2 or other chromatin regulators is an important question for future studies." (PMID 36309692, 2022). "In summary, overexpression of TASOR would substantially reduce the transcription in cancer cells (hence their proliferation) while increasing the renewal of the normal cells." (PMID 33302383, 2020). "In addition, we previously uncovered in a two-hybrid screen an association between TASOR and ARID1A, a SWI/SNF subunit gene that is very frequently mutated in cancers." (PMID 36309692, 2022). "We delineated the molecular mechanisms by which TASOR overexpression and ALG13 silencing would selectively affect the cancer cells with little consequences for the normal cells." (PMID 33302383, 2020). "For now, no cancer-related functional pathway has been assigned to TASOR and FAM27C, with the present study being the first (to our knowledge) to discuss their implications in the development of ccRCC." (PMID 33302383, 2020).
tumor (3 papers, 2020 to 2025). "It is noteworthy that TASOR was originally identified as a protein interacting with the famous Rb (retinoblastoma protein) tumor suppressor." (PMID 36309692, 2022). "Using data from the National Cancer Institute Clinical Proteomic Tumor Analysis Consortium (CPTAC) we further demonstrated that ZNF638, TASOR, MPHOSPH8, SETDB1 proteins were significantly enriched in GBM versus normal brain tissue." (PMID 40091830, 2025). "However, most of our transcriptomic results (including tumor heterogeneity, activation of chemokine and VEGF signaling pathways, major roles of TASOR and ALG13) can explain functional and clinical observations of other authors." (PMID 33302383, 2020).
infection (1 paper, 2025). The state of being infected such as from the introduction of a foreign agent such as serum, vaccine, antigenic substance or organism. "Immunoblot analysis showed more efficient degradation of SAMHD1 and TASOR with the Vpx-P41A mutant, suggesting that disrupting the Pro41 hydroxylation site enhances Vpx stability during infection, leading to more effective antagonism of host restriction factors and increased viral infectivity." (PMID 40522994, 2025).
TASOR also shares sentences with these, for which no sentence is quoted: Clear cell renal cell carcinoma (1 paper); colorectal adenocarcinoma (1); viral infection (1).